IL22 (interleukin 22)
Diseases named in the same sentence as IL22 in open-access papers (continued):
Sharing a sentence is not in itself a finding about the gene and the disease.
psoriasis (continued). "When present with IL-22 or TNF-a, IL-17 induced the production of an antimicrobial protein that played a protective role when psoriasis lesions were combined with bacterial or fungal infections." (PMID 39480805, 2024). "In parallel, the mRNA expression levels of psoriasis-related cytokines, such as IL-17A, IL-23, IFN-γ and IL-22 greatly increased in immune-related skin reactions to anti-PD-1." (PMID 38495872, 2024). "TNFα, IL-17, and IL-22 stimulate ERK phosphorylation, leading to the increased expression of crucial psoriasis mediators such as IL-36α and IL-36γ." (PMID 38674130, 2024). "In this context, an increased transcript level of pro-inflammatory factors such as IL-6 is the essential hallmark of the disease in addition to further described cytokines important in psoriasis pathogenesis such as TNF-alpha, IL-22 and IL-17." (PMID 37707681, 2024). "As TH17 cells have been described as main contributors for the development of psoriasis pathology, a psoriasis model was induced by treating HSEs with a TH17-derived cytokine mix (IL-17A and IL-22, 30 ng/ml each)." (PMID 38251799, 2024). "Remarkably, treatment of 17A-Lytaca markedly decreased the mRNA expression of IL-17A and its downstream psoriasis-related inflammatory cytokines in the skin lesion, including IL-6, CCL-20, and IL-22, compared with the positive group." (PMID 38396109, 2024). "Th17 cells are critically involved in the pathogenesis of psoriasis by producing pro-inflammatory cytokines such as TNF-α, IL-17 and IL-22, which stimulate hyperproliferation and altered keratinocyte differentiation in psoriasis." (PMID 39331218, 2024). "HaCaT cells co‐stimulated with interleukin (IL)‐17, IL‐22, tumor necrosis factor‐alpha (TNF‐α), IL‐1α, and oncostatin M (M5) were used as an in vitro cell model of psoriasis." (PMID 39167035, 2024). "This interruption in cytokine signaling effectively reduces the inflammatory response mediated by cytokines such as IL-4, IL-13, IL-31, IL-22, and IFN-γ, which are critical in conditions like AD, psoriasis, and alopecia areata (AA)." (PMID 39610670, 2024). "The Multi-Analyte Flow Assay test showed that IMQ-induced psoriasis in mice had a notable effect on reducing IFN-γ, TNF-α, IL-9, IL-17F, IL-22, and IL-17A psoriasis-related inflammatory cytokines in the APLNs, Cal/Bms, and FA groups." (PMID 39534602, 2024). "In the case of psoriasis, it has been identified that specific cytokines (TNF-α, IL-17, and IL-22) secreted by subsets of T-cells are responsible." (PMID 39712184, 2024). "Circulating T cells in psoriasis patients triggered by LL37 produce IFN-γ, IL-17, IL-22, and CXCL8 as well as upregulate perforins and granzyme B." (PMID 38642273, 2024). "Although inflammatory mediators like IL-22 and IL-17 have different functions in IBD and psoriasis as this is also evident in the targeted treatment response, IL-23 and TNF-α seem to play a crucial part in promoting inflammatory response in both disorders." (PMID 39463646, 2024). "Patients suffering from both psoriasis and CVD have increased serum levels of Th17-dependent cytokines IL-6, IL-21, IL-22 and TNF." (PMID 39200092, 2024). "Although anti-IL-17 and anti-IL-17 receptor antibodies are effective for psoriasis, the blockade of TL1A-DR3 interaction can also be an alternative therapeutic approach by repressing IL-22 overproduction." (PMID 38348035, 2024). "Mice with TPA-induced psoriasis showed increased gene expression of both the Th17 transcription factor, RORC, and Th17-produced cytokines, Il17a, Il17e, Il17f, and Il22, in the ear tissue compared with those in normal mice." (PMID 39765869, 2024). "T cells from psoriasis patients had a greater IFN-γ, IL-17 and IL-22 production due to an increased CD1a response compared to healthy individuals." (PMID 38827737, 2024).
psoriasis (continued). "Wang and colleagues reported higher lncRNA-XIST levels in patients with psoriasis compared to healthy controls and a positive correlation between lncRNA-XIST levels and the PASI score, as well as TNF-α, IL-17, and IL-22 levels." (PMID 38927529, 2024). "Effectively, Sialostatin L didn’t show any significant inhibition of IL-6, although psoriasis-related pro-inflammatory cytokines (TNF-α, IL-22, IL-23/IL-17) expression was reduced." (PMID 38444844, 2024). "For example, increased K17 expression upregulates the expression of multiple proinflammatory cytokines and chemokines, including IFN-γ, IL-22, and CXCL1, and plays an important role in the development of psoriasis." (PMID 38730319, 2024). "Tissue-resident memory T (TRM) cells also contribute significantly to the pathogenesis and recurrence of psoriasis, as the sustained presence of IL-17-secreting CD8+ T cells and IL-22-secreting CD4+ T cells can result in chronic inflammatory plaque formation." (PMID 38596682, 2024). "Targeted anti-psoriasis therapies namely biological agents have been developed with the recognition of TNF-a, IL-23/Th17 axis and IL-22/Th22 pathway, representing better efficacy as well as relative safety." (PMID 37942312, 2023). "NB-UVB treatment suppresses serum levels of psoriasis-driving cytokines, such as tumor necrosis factor (TNF)-α, IL-8, IL-12, IL-17, IL-22, IL-23, and IL-34 and elevates the levels of IL-10, an anti-inflammatory cytokine, in patients with psoriasis." (PMID 36928592, 2023). "The nanoformulations of CUR were majorly able to decrease psoriasis inflammatory symptoms, PASI, TNF-α, IL-17, IL-22 and IL-1β levels, C-C chemokine receptor type 6 (CCR6) expression, the proliferation of psoriatic cells and occurrence of psoriatic lesions." (PMID 36678859, 2023). "The combination of TNF-α, IL-1α, IL-17A, IL-22, and OSM (termed as M5) has been shown to induce psoriasis-like changes, including cell inflammation and increased cell proliferation in cultured keratinocytes." (PMID 36999136, 2023). "Psoriasis is centered on the overproduction of Th1‐ and Th2‐related cytokines (e.g., interleukin [IL]‐23, IL‐17, TNF‐α, IL‐22), which is involved in the occurrence and development of its pathogenesis." (PMID 37647442, 2023). "The common occurrence of psoriasis on the skin primarily involves an inflammatory response involving IFN-α, IFN-γ, IL-1, IL-6, IL-17, IL-22, and IL-23 from dendritic cells, macrophages, and helper T cells (Th cells)." (PMID 37629529, 2023). "Through intragastric administration, CUR can alleviate psoriasis‐like lesions of mice by decreasing PASI scores, reducing the level of IL‐6, IL‐17A, IL‐22, IL‐23, TNF‐α, and TGF‐β1, promoting the expression of IL‐10." (PMID 37647442, 2023). "Statistically significant correlations were also observed between baseline IL-17A, IL-17F, and IL-22 levels and baseline PASI score as well as between IL-17A and IL-17F levels and BSA affected by psoriasis." (PMID 37587493, 2023). "At baseline, serum levels of effector cytokines (IFN-γ, IL-17 and IL-22) and proinflammatory cytokines (IL-6, TNF-α) were higher in psoriasis patients relative to healthy controls." (PMID 37681925, 2023). "We do not see a statistically meaningful correlation between circulating levels of IL-4, IL-12, IL-22, IL-23, IL-35, IL-36 and TGF-β with the development of psoriasis." (PMID 37883350, 2023). "The subsets of T lymphocytes intensely studied in psoriasis are CD4+ T helper 1, T helper 17, and T helper 22, which secrete TNFα/IFNγ, IL-17/Il-22, as well as IL-22, respectively." (PMID 37631384, 2023). "Important cytokines like IL-17, IL-22, IL-23, and TNF-α are involved in the pathogenesis of psoriasis, as well as other crucial transduction pathways like the NF-κB and STAT signaling pathways." (PMID 37828492, 2023).
psoriasis (continued). "We examined the expression of cytokines previously reported to be involved in psoriasis, and found that IL17A, IL17F, IL26, CCL20, CXCL13, IL22, and IL23R were specifically expressed by Tc17 cells." (PMID 37308489, 2023). "We further showed induction of CXCL12 in HMEC-1 cells by either mixture of pro-inflammatory cytokines (IL-17A, IL-22, TNF, IL-1α, and oncostatin M), or serum from active psoriasis patients." (PMID 37736772, 2023). "A research on psoriasis pathogenesis revealed that STAT1 directly antagonized STAT3 and repressed IL-22 expression." (PMID 37391858, 2023). "Normal human epidermal keratinocytes (NHEKs), HaCaT cells, and Ker-CT cells stimulated with M5 (IL-17A, IL-22, IL-1α, oncostatin M, and TNF-α) were used to establish a psoriasis model in vitro." (PMID 35586566, 2022). "Our data show that eCIRP expression was increased in the sera of psoriasis patients and imiquimod- (IMQ-) induced psoriatic mice and cells stimulated with proinflammatory cytokines (IL-1α, IL-17A, IL-22, oncostatin M, and TNF-α; mix M5)." (PMID 36110097, 2022). "Thus, targeting IL-22 might be used as a maintenance treatment to avoid psoriasis relapse." (PMID 35911703, 2022). "For example, in mouse psoriasis models RORγt positive ILC3 account for the production of the proinflammatory IL-17A and the potent keratinocyte growth factor IL-22 and levels of this cell type are increased in human psoriatic skin." (PMID 35337918, 2022). "The levels of inflammatory TH17 cytokines (IL-17A, IL-22 and IL-23) and TH1 cytokines (IL-1β, IFN-γ and TNF-α) were also measured in the skin; psoriasis is considered to be regulated by TH17 and TH1 responses." (PMID 35562873, 2022). "Next, we examined IL‐22 and IFN‐γ responses to AOAH in a larger cohort of healthy adults and individuals with psoriasis." (PMID 34913478, 2022). "CD8+ TRM in the skin of patients suffering from psoriasis express the IL23 receptor, and, therefore, are able to produce pro-inflammatory interleukin (IL)-17 and IL-22 in the psoriatic skin, even for many months after remission." (PMID 35886201, 2022). "In psoriasis, the cytokine is predominantly released by CD4 cells, whereas CD8 cells appear to be the primary producers of IL-22 in AD." (PMID 36359220, 2022). "Remarkably, the ratios of autoantibodies to cytokines of IL-22, IL-17A, and IFN-γ were significantly decreased, whereas the ratio of anti-IL-8 antibody to IL-8 was elevated in patients with psoriasis." (PMID 36118416, 2022). "Our results showed that spleen weight and cytokine levels, including IL-17A, IL-22, IL-23, IL-6, and IFN-γ, increased in the IMQ-induced psoriasis-like dermatitis mice." (PMID 35682849, 2022). "Together, these findings showed that the major profile of ACAAs is at a normal range except anti-IL-22 and anti-IL-15 antibodies, and the titers of single ACAA hardly correlated with psoriasis severity." (PMID 36118416, 2022). "In the imiquimod induced psoriasis mice model, CD4+ and TCR γδ T cells are believed to be major sources of IL-17 and IL-22." (PMID 35629363, 2022). "Coptisine reduced the severity of psoriasis-like skin lesions, decreased epidermal hyperplasia and the levels of inflammatory cytokines TNF-α, IL-17, and IL-22." (PMID 35209199, 2022). "The common occurrence of psoriasis on the skin primarily involves an inflammatory response involving IFN-α, IFN-γ, IL-1, IL-6, IL-17, IL-22, IL-23 from dendritic cells, macrophages, and helper T cell (Th cells)." (PMID 35566346, 2022). "IL-6 and IL-22 are Th17-related cytokines that activate STAT3 synergistically and contribute to the pathological development of psoriasis." (PMID 35351863, 2022). "In vitro studies confirmed that topical application of a natural compound combination of herbs at a dose 10 μM, which included emodin, lowered the proliferation rate of IL-22-stimulated keratinocytes and relieved IMQ-induced psoriasis-like dermatitis." (PMID 35163855, 2022).
psoriasis (continued). "The pathogenesis of psoriasis includes excessive proinflammatory cytokines, such as IFN-γ, TNF-α, IL-17, IL-22, and IL-23, among which IL-17A plays a key role." (PMID 35745784, 2022). "Increased K17 expression in psoriatic lesional skin upregulates the expression of multiple proinflammatory cytokines and chemokines, including IFN-γ, IL-22, and CXCL1, and plays an important role in the development of psoriasis." (PMID 35178048, 2022). "In patients with psoriasis, an increase in the CD8 and CD69, IL-17A and IL-22 immunoreactive area in the epidermis was found, but it did not change significantly in the dermis compared to the control group." (PMID 35886201, 2022). "Circ_0061012 accelerated IL-22-induced proliferation and metastasis in HaCaT cells through enhancing GAB1 expression via sponging miR-194-5p in psoriasis." (PMID 33393621, 2021). "IL-6 and IL-22, which are potent STAT3 activators, are known for their synergistic action with IL-17A in the pathogenesis of psoriasis." (PMID 34445513, 2021). "Taken together, the ex vivo psoriasis skin model generated by tape stripping and stimulation with psoriasis cytokines (IL-17A, TNF-α and IL-22) turned out as a useful psoriasis ex vivo model, with psoriasin, BD2 and GLUT1 as psoriasis markers." (PMID 33801280, 2021). "Due to the essential role in forwarding the IL-23/Th17 axis and IL-22/Th22 pathway signals into cell, JAK/STAT pathway has received increasing attention recently in psoriasis." (PMID 34975883, 2021). "In the active stage of psoriasis,the expression of IFN-γ, IL-17A and IL-22 in CD4+ and CD8+ T cells in the epidermis is increased." (PMID 34295334, 2021). "Previous studies have reported that several cytokines, including IL-17, IL-22, IL-23, and tumor necrosis factor-α (TNF-α), are expressed highly in the epidermis of patients with psoriasis or the imiquimod-induced mouse model." (PMID 34281197, 2021). "Although the mouse model showed that epithelial hyperplasia caused by IL-23 is also dependent on IL-22, and subsequently IL-22/Th22 axis theses have been developed, still its therapeutic blockade has not been successful, thus IL-22 is probably not a crucial part of the psoriasis pathogenesis." (PMID 34769005, 2021). "With respect to the inflammatory cytokines involucrate in the development of psoriasis, EGCG treatment reduced the level of IL-23, IL-22, IL-17F, and IL-17A." (PMID 34943117, 2021). "In this study, a combination of IL-1α, IL-17A, IL-22, oncostatin M, and TNF-α (mix M5) was used to trigger psoriasis-like changes in NHEK cells in vitro." (PMID 34314383, 2021). "Psoriasis is a chronic inflammatory, immune-mediated disease which is induced by many pro-inflammatory cytokines, such as IL-17A, TNF-a, IL-22 and IL-23." (PMID 34992498, 2021). "Regarding its function in psoriasis, STAT3 activation in psoriatic keratinocytes occurs by IL-17, IL-19, IL-21, IL-22, visfatin, and IL-36." (PMID 34679602, 2021). "This study was performed to observe the effects of FZHFZY on epidermal differentiation in IL-17A/IL-22/IFN-γ/TNF-α stimulated HaCaT cells and a mouse model of IMQ-induced psoriasis." (PMID 34456715, 2021). "By addition of the psoriasis cytokines from the in vitro experiments (IL-17A, TNF-α, IL-22, 20 ng/mL each), an inflammatory milieu typical for psoriasis was simulated." (PMID 33801280, 2021). "In our study, there is downregulated expression of loricrin, filaggrin and involucrin, but elevated expression of keratin 5, keratin 14 and keratin 15 in IL-17A/IL-22/IFN-γ/TNF-α–induced HaCaT cells and in mice with IMQ-induced psoriasis." (PMID 34456715, 2021). "We obtained a psoriasis-like phenotype of HPK with a combination of physiological concentrations of IL-17A, IL-22 and TNF-α (20 ng/mL each)." (PMID 33801280, 2021).
psoriasis (continued). "The AZT treatment reduces the level of several pro-inflammatory cytokines (IL-17, IL-22, and IL-23) and accumulation of DCs, CD4+T cells, CD8+T cells, and Th17 cells in the skin of mice suffering from imiquimod-induced psoriasis." (PMID 33510592, 2021). "The pathogenesis of psoriasis is extremely complex and involves numerous immune and inflammatory mediators, including IL-1α, TNF-α, IL-17A, and IL-22." (PMID 34314383, 2021). "Several cytokines are used for the generation of psoriasis-like HPK, i.e., IL-17A, TNF-α, IL-36γ, oncostatin, IFN-γ, IL-22 and IL-1α." (PMID 33801280, 2021). "We further explored the expression of PI3K isoforms in response to IL-22, IL-17A, TNF-α, and IFN-γ, pro-inflammatory cytokines deeply involved in psoriasis pathogenesis." (PMID 34685616, 2021). "Gene expression analysis in paw skin demonstrated increased expression of Tnf, Il1b, Il17a, and Il22 in mice injected with IL-23 EEV, consistent with the psoriasis-like changes seen on histology of the ears." (PMID 33983951, 2021). "In summary, treatment of HPK with the cytokines IL-17A, IL-22 and TNF-α results in a psoriasis-like phenotype." (PMID 33801280, 2021). "HaCaT cells were stimulated with a cocktail of five proinflammatory cytokines (M5), including IL-1α, IL-17A, IL-22, oncostatin M, and TNF-α that has been demonstrated as an in vitro model of psoriasis." (PMID 33149756, 2020). "The number of CD8+CD103+ TRM in the psoriatic epidermis correlates with epidermal thickness, and psoriatic skin-derived CD103+TRM produce IFN-γ, IL-17A, and IL-22, suggesting the important roles of TRM in the formation of psoriasis." (PMID 32823524, 2020). "In active psoriasis, we observe increased expression of IL17A, IL22 and IFN-γ in the effector T CD4+ and CD8+ cells of the epidermis in the immediate vicinity of keratinocytes, whereas cutaneous T cells show less activity of these genes." (PMID 31963581, 2020). "During psoriasis development, the increased expression of inflammatory cytokines, such as tumor necrosis factor (TNF)-α, interleukin (IL)-6, IL-17A, and IL-22 triggers uncontrolled inflammatory states and activates keratinocyte hyperproliferation." (PMID 32515468, 2020). "KRT6, IL‐17 and IL‐22 protein within psoriasis lesions was significantly decreased, while KRT10 protein in psoriasis lesions was increased by ozone treatment." (PMID 32168425, 2020). "In vitro, the expression of EZH2 and H3K27me3 was stimulated in human keratinocytes treated with mixture of psoriasis-related cytokines pool (TNF-α, IFN-γ, IL-17A, and IL-22)." (PMID 33011750, 2020). "In this study, HPKs were treated with IFN-γ, IL-17A, IL-22 and TNF-α, to generate a psoriasis-like phenotype." (PMID 32316273, 2020). "Distinct IL-22-producing CD4+ and CD8+ T-cell populations were significantly increased in AD skin compared with psoriasis." (PMID 32075269, 2020). "IL-22 is known to play a role in multiple diseases such as inflammatory bowel disease (IBD), psoriasis, arthritis and cancer." (PMID 33003458, 2020). "T cell-associated gene (LCK and TRCB1) and inflammatory gene (IL17, IL22 and IFN-γ) activity remains increased in the skin after psoriasis lesions, at least three months after the onset of the treatment with TNF-α inhibitors." (PMID 31963581, 2020). "Immune-related cells such as dendritic cells (DCs) and macrophages, in addition to Toll-like receptors and cytokines such as interferon (IFN)α, TNFα, IFNɤ, IL12, IL22, IL23, and IL17, are related to the pathogenesis of psoriasis." (PMID 33050592, 2020). "Psoriasis recurs in previously affected sites, and CD8+ TRM enriched in the resolved lesion preferentially produces IL-17 and IL-22 upon restimulation." (PMID 32823524, 2020). "IL-22-induced keratinocyte hyperproliferation is regulated by the PI3K/Akt/mTOR signaling pathway, and targeting this pathway is a potent approach for psoriasis treatment." (PMID 33149756, 2020).